CWF19L1 (CWF19 like cell cycle control factor 1)
Synonyms: C19L1; FLJ10998; hDrn1; SCAR17
Tractability: Small molecule: a structure with a bound ligand is known. PROTAC: ubiquitination databases record sites on it; its protein half-life has been measured.
Gene: Protein-coding gene on chromosome 10 (100,232,296 to 100,267,684, reverse strand). Ensembl gene ENSG00000095485.
Subcellular location (Human Protein Atlas): Golgi apparatus; Nucleoplasm
Gene Ontology:
Molecular function: protein binding; RNA lariat debranching enzyme activator activity
Biological process: mRNA splicing, via spliceosome
Cellular component: nucleus; post-mRNA release spliceosomal complex
Genetic constraint (gnomAD): Loss-of-function variants: 42 observed, 45.11 expected, observed/expected ratio (o/e) 0.93, 90% interval 0.73 to 1.2. The upper end of that interval is the gene's LOEUF score, 1.2, which puts it in group 5 of 6, group 1 being the genes least tolerant of losing a copy. Missense variants: 446 observed, 490.69 expected, observed/expected ratio (o/e) 0.91, 90% interval 0.84 to 0.98. Synonymous variants: 152 observed, 176.74 expected, observed/expected ratio (o/e) 0.86, 90% interval 0.75 to 0.98.
Gene-disease validity (ClinGen):
ClinGen rates the evidence that CWF19L1 causes each of these diseases.
autosomal recessive cerebellar ataxia (autosomal recessive): Definitive.
Homologues: Orthologues: chimpanzee CWF19L1 (99% identical), macaque CWF19L1 (96% identical), pig CWF19L1 (95% identical), dog CWF19L1 (94% identical), guinea pig CWF19L1 (91% identical), rat Cwf19l1 (90% identical), mouse Cwf19l1 (89% identical), tropical clawed frog cwf19l1 (69% identical), zebrafish cwf19l1 (58% identical), Caenorhabditis elegans cwf-19L1 (42% identical), Drosophila melanogaster CG7741 (38% identical). Paralogues in human: CWF19L2 (21% identical).
Diseases named in the same sentence as CWF19L1 in open-access papers:
CWF19L1 is named in the same sentence as 16 diseases in open-access papers, as found by Europe PMC text mining. Sharing a sentence is not in itself a finding about the gene and the disease. The quoted sentences say what the papers report.
cerebellar ataxia (4 papers, 2018 to 2025). A neurological syndrome characterized by clumsy and uncoordinated movement of the limbs, trunk, and cranial muscles. "In the KO network, LHX3 was in the same subnetwork as CWF19L1, which is a gene commonly associated with spinocerebellar ataxia." (PMID 40258535, 2025). "CWF19L1 has been reported to be associated with a similar human phenotype, such as cerebellar ataxia and intellectual disability." (PMID 36357319, 2022). "A study only revealed the role of CWF19L1/hDrn 1 in an intron turnover after hDbr1 splicing, and a report corroborates that loss‐of‐function mutations in CWF19Ll lead to early onset cerebellar ataxia and (progressive) cerebellar atrophy." (PMID 32508030, 2020). "Mutations in CWF19L1 (chromosome 10; locus 91) have been associated with spinocerebellar ataxia and intellectual disability." (PMID 29844566, 2018). "Here, we report novel compound heterozygous variants of CWF19L1 in a Chinese family with progressive ataxia and mental retardation of unknown etiology by analyzing clinical characteristics and genetic variations." (PMID 36357319, 2022). "CWF19L1 is responsible for spinocerebellar ataxia, autosomal recessive 17, which presents with cerebellar ataxia, and atrophy." (PMID 36357319, 2022).
autosomal recessive cerebellar ataxia (2 papers, 2022 to 2024). "Two novel heterozygous variants of the CWF19L1 gene were identified in the CWF19L1 gene associated with autosomal recessive cerebellar ataxia." (PMID 36357319, 2022).
colon carcinoma (1 paper, 2024). "Subsequently, we evaluated the efficacy of CWF19L1-overexpressing CTLs in targeting murine B16/F10 melanoma cells, MC38 colon carcinoma cells, and Panc02 pancreatic tumor cells pulsed with ovalbumin peptides (OVA257–264)." (PMID 39542248, 2024).
developmental delay (1 paper, 2022). "Our results suggest that CWF19L1 variants may be a novel cause of recessive ataxia with developmental delay." (PMID 36357319, 2022).
fatty liver (1 paper, 2018). "These included genes like CWF19L1, which was previously shown to act in fatty liver and metabolic diseases." (PMID 29587401, 2018).
glioma (1 paper, 2020). A benign or malignant brain and spinal cord tumor that arises from glial cells (astrocytes, oligodendrocytes, ependymal cells). "In conclusion, the expression of CWF19L1 is negatively correlated with the WHO grading of glioma, while the high expression of CWF19L1 is associated with a better survival prognosis." (PMID 32508030, 2020). "The data analysis revealed that CWF19L1 is associated with a better prognosis in patients with glioma." (PMID 32508030, 2020). "We suggest that CWF19L1 may be associated with a better prognosis of glioma (P < .0006)." (PMID 32508030, 2020). "These analyses indicate that CWF19L1 is a promising independent biomarker for the diagnosis of glioma." (PMID 32508030, 2020). "RNAseq databases from The Cancer Genome Atlas (TCGA) and CGGA cohorts were used to reveal the CWF19L1 and glioma grade correlation." (PMID 32508030, 2020). "In the present study, the in vitro experiments revealed the efficacy and mechanism of action AQB in combination with palbociclib on cell cycle inhibition in glioma cell lines, with a high expression of HOTAIR and EZH2, and a low expression of CWF19L1." (PMID 32508030, 2020). "The combination of AQB and palbociclib inhibitors has a more pronounced suppression effect on the cell cycle, especially gliomas with high expression of HOTAIR and EZH2 and low expression of CWF19L1." (PMID 32508030, 2020).
hereditary ataxia (1 paper, 2024). An instance of an atactic disorder that is caused by an inherited genomic modification in an individual. "In addition to its association with hereditary ataxia and tumor cell proliferation, CWF19L1 is also implicated in mRNA processing, although its precise role in splicing remains unclear." (PMID 39542248, 2024). "CWF19L1, initially identified as a hereditary ataxia-related molecule, has recently garnered attention for its effects in cancer." (PMID 39542248, 2024).
type 2 diabetes (1 paper, 2023). "Ten VAT-specific candidate genes were associated with type 2 diabetes after Bonferroni correction, including five causal genes supported by SMR and co-localisation: PABPC4 (1p34.3); CCNE2 (8q22.1); HAUS6 (9p22.1); CWF19L1 (10q24.31); and CCDC92 (12q24.31)." (PMID 37540242, 2023). "Besides, genetically elevated expression of CCNE2 on 8q22.1, HAUS6 on 9p22.1, CWF19L1 on 10q24.31, CCDC92 on 12q24.31 and DNAH10OS on 12q24.31 showed protective effects on type 2 diabetes risk." (PMID 37540242, 2023). "However, there have been no experimental studies that link the expression of CWF19L1 with type 2 diabetes." (PMID 37540242, 2023).
tumor (3 papers, 2020 to 2024). "Remarkably, CWF19L1-overexpressing OT-I CTLs demonstrated significantly enhanced killing specificity against all three types of tumor cells compared to control OT-I CTLs (A−D)." (PMID 39542248, 2024). "The expression level of CWF19L1 was significantly correlated with the tumor grade (TCGA P < .0006 and CGGA P < .002)." (PMID 32508030, 2020). "We performed protein mass spectrometry to identify AQB upregulated tumor suppressor genes and confirmed that CWF19L1 is regulated by H3K27ac through chromatin immunoprecipitation‐quantitative PCR results." (PMID 32508030, 2020). "Moreover, CWF19L1 overexpression facilitated CTLs-mediated anti-tumor immunity, suggesting its potential as a target for immunotherapy to bolster immune responses against cancer." (PMID 39542248, 2024). "AQB has also been found to induce the expression of tumor suppressor genes, including CWF19-like cell cycle control factor 1 (CWF19L1) which controls cell cycle progression by modulating the stability of cyclin-dependent kinases CDK4/6." (PMID 38366205, 2024). "Hence, we speculated that CWF19L1 also affects tumor formation and proliferation." (PMID 32508030, 2020). "In kidney renal clear-cell carcinoma, CWF19L1 may enhance cancer progression by increasing gene expression through RNA editing sites in the 3′ UTR and promoting tumor cell proliferation." (PMID 39542248, 2024).
cancer (1 paper, 2024). A tumor composed of atypical neoplastic, often pleomorphic cells that invade other tissues. "Our findings unveil previously undocumented functions of CWF19L1 in alternative splicing and its involvement in the regulation of antitumor immunity, highlighting its potential as a therapeutic target for novel cancer immunotherapies." (PMID 39542248, 2024). "Our findings suggest CWF19L1 as a potential therapeutic target in cancer immunotherapy." (PMID 39542248, 2024).
CWF19L1 also shares sentences with these, for which no sentence is quoted: metabolic disease (2 papers); Ataxia (1); Cerebellar atrophy (1); Intellectual disability (1); melanoma (1); promyelocytic leukemia (1).